RNASEH1 (ribonuclease H1)
Description:
Endonuclease that specifically degrades the RNA of RNA-DNA hybrids. Plays a role in RNA polymerase II (RNAp II) transcription termination by degrading R-loop RNA-DNA hybrid formation at G-rich pause sites located downstream of the poly(A) site and behind the elongating RNAp II.
Synonyms: RNH1; H1RNA; PEOB2
Tractability: Small molecule: a structure with a bound ligand is known; a high-quality ligand is known; it belongs to a druggable protein family. PROTAC: ubiquitination databases record sites on it; a small molecule that binds it is known.
Target class: Enzyme; Hydrolase
Gene: Protein-coding gene on chromosome 2 (3,541,430 to 3,558,371, reverse strand). Ensembl gene ENSG00000171865.
Subcellular location: Cytoplasm
Subcellular location (Human Protein Atlas): Cytosol; Nucleoplasm
Pathways (Reactome):
DNA Replication: Strand-asynchronous mitochondrial DNA replication
Gene Ontology:
Molecular function: protein binding; RNA-DNA hybrid ribonuclease activity; nucleic acid binding; RNA binding; RNA nuclease activity; magnesium ion binding
Biological process: DNA replication, removal of RNA primer; mitochondrial DNA replication; RNA catabolic process
Cellular component: mitochondrion; mitochondrial matrix; nucleus; cytoplasm
Genetic constraint (gnomAD): Loss-of-function variants: 19 observed, 23.97 expected, observed/expected ratio (o/e) 0.79, 90% interval 0.55 to 1.16. The synonymous counts are far from expectation, so gnomAD's model fits this gene poorly and the ratio says little. Missense variants: 278 observed, 283.09 expected, observed/expected ratio (o/e) 0.98, 90% interval 0.89 to 1.09. Synonymous variants: 138 observed, 107.85 expected, observed/expected ratio (o/e) 1.28, 90% interval 1.11 to 1.47.
Gene-disease validity (ClinGen):
ClinGen rates the evidence that RNASEH1 causes each of these diseases.
Leigh syndrome (autosomal recessive): Limited. A progressive neurological disease defined by specific neuropathological features associating brainstem and basal ganglia lesions.
Homologues: Orthologues: chimpanzee RNASEH1 (99% identical), macaque RNASEH1 (94% identical), dog RNASEH1 (83% identical), rabbit RNASEH1 (82% identical), mouse Rnaseh1 (78% identical), pig RNASEH1 (78% identical), guinea pig RNASEH1 (78% identical), rat Rnaseh1 (77% identical), tropical clawed frog rnaseh1 (56% identical), zebrafish rnaseh1 (49% identical), Caenorhabditis elegans rnh-1.0 (37% identical), Drosophila melanogaster rnh1 (37% identical).
Diseases named in the same sentence as RNASEH1 in open-access papers:
RNASEH1 is named in the same sentence as 37 diseases in open-access papers, as found by Europe PMC text mining. Sharing a sentence is not in itself a finding about the gene and the disease. The quoted sentences say what the papers report.
cerebellar ataxia (4 papers, 2017 to 2024). A neurological syndrome characterized by clumsy and uncoordinated movement of the limbs, trunk, and cranial muscles. "Among the nuclear genes associated with mtDNA maintenance disorders, RNASEH1 mutations produce a homogeneous phenotype, with progressive external ophthalmoplegia (PEO), ptosis, limb weakness, cerebellar ataxia, and dysphagia." (PMID 35711919, 2022). "Pathological mutations in RNASEH1 have been described in patients with mitochondrial depletion and deletion syndromes characterized by CPEO, cerebellar ataxia, and dysphagia." (PMID 32082360, 2019). "Clinically, RNASEH1-linked mitochondrial disease is relatively homogenous, comprising PEO, cerebellar ataxia, dysphagia, and proximal muscle weakness." (PMID 28508084, 2017). "RNASEH1-related mitochondrial disease was characterized by PEO (100%), cerebellar ataxia (57%), and dysphagia (50%)." (PMID 28508084, 2017).
breast carcinoma (2 papers, 2021 to 2025). "The growth of Thrap3 knockdown MCF7 breast cancer cell lines was significantly inhibited, and RNaseH1 expression restored the cell proliferation capacity." (PMID 34697388, 2021).
chronic progressive external ophthalmoplegia (2 papers, 2023 to 2025). "Human patients carrying RNASEH1 mutations often exhibit adult-onset muscle weakness accompanied by progressive external ophthalmoplegia due to defective mitochondrial function." (PMID 40568127, 2025).
hepatocellular carcinoma (2 papers, 2022 to 2024). A malignant tumor that arises from hepatocytes. "In hepatocellular carcinoma (HCC), a novel prognostic signature composed of 6 key lactate metabolism-related genes (FKTN, PDSS1, PET117, PUS1, RARS1, and RNASEH1) was developed to predict the survival and tumor microenvironment of HCC patients." (PMID 38529390, 2024). "In hepatocellular carcinoma (HCC), transcriptomic data revealed a lactate metabolism-related gene signature (LMRGS) based on the expression of six genes (FKTN, PDSS1, PET117, PS1, RARS1, and RNASEH1)." (PMID 36713558, 2022).
mitochondrial encephalomyopathy (2 papers, 2020 to 2022). A heterogenous group of disorders characterized by alterations of mitochondrial metabolism that result in muscle and nervous system dysfunction. "Patients with RNASEH1 mutations were diagnosed as mitochondrial encephalomyopathy with PEO and marked cerebellar syndrome." (PMID 33396418, 2020).
ovarian carcinoma (2 papers, 2022 to 2023). A malignant neoplasm originating from the surface ovarian epithelium. "To our expect, we observed an expression pattern of high A3B but low RNASEH1 in prexasertib (Chk1i) sensitive ovarian cancer cell lines, in contrast to that of prexasertib-resistant cell lines." (PMID 37270643, 2023).
B-cell lymphoma (1 paper, 2025). "RNASEH1 could prevent replication stress and DNA damage by removing R-loops, and dysfunction of RNASEH1 is closely related to the progression of various cancers, including gastric cancer, B-cell lymphoma, and melanoma." (PMID 41019085, 2025).
cardiomyopathy (1 paper, 2022). A disease of the heart muscle or myocardium proper. "From 8 weeks onwards, Rnaseh1 knockout animals developed a gradual increase in the heart to body weight ratio indicating progressive cardiomyopathy." (PMID 35947649, 2022).
Fanconi anemia (1 paper, 2020). Fanconi anemia (FA) is a hereditary DNA repair disorder characterized by progressive pancytopenia with bone marrow failure, variable congenital malformations and predisposition to develop hematological or solid tumors. "Importantly, this increase was reduced by RNaseH1 overexpression, proving that TDP-43 depletion is responsible for an accumulation of the Fanconi Anemia repair factor caused by R-loop accumulation." (PMID 33301444, 2020).
lymphoma (1 paper, 2022). A malignant (clonal) proliferation of B- lymphocytes or T- lymphocytes which involves the lymph nodes, bone marrow and/or extranodal sites. "The high expression of RNaseH1 leads to R-loop degradation, the process which subsequently reduces cytosolic DNA and inhibits type I IFN-dependent rejection of lymphoma cells." (PMID 36428700, 2022).
male infertility (1 paper, 2024). The inability of the male to effect fertilization of an ovum after a specified period of unprotected intercourse. "The accumulation of R-loops induced by the deletion of Rnaseh1 caused transcriptional dysfunction of meiotic genes and impaired meiotic recombination by altering the recruitment of RAD51 and DMC1, resulting in male infertility." (PMID 38858601, 2024).
Mitochondrial myopathy (1 paper, 2019). "Our results demonstrate the pathogenicity of two new RNASEH1 variants found in a patient with PEO syndrome, multiple deletions, and mild mitochondrial myopathy." (PMID 31258551, 2019). "In conclusion, our data support the pathogenicity of the two RNASEH1 variants found in a patient with PEO syndrome, multiple deletions, and mild mitochondrial myopathy, phenotypic traits that are characteristic of other patients with mutations in the same gene." (PMID 31258551, 2019). "Here, we report the case of a patient diagnosed with mild mitochondrial myopathy characterized by PEO and multiple mtDNA deletions caused by two previously unreported mutations in the RNASEH1 gene, one located in the catalytic domain and the other in the RNase H1 connection domain." (PMID 31258551, 2019).
Myalgia (1 paper, 2025). "Second, APC, ENO3, ACAD9, RNASEH1, FKTN, DYSF, and ATP2A1 are associated with Myalgia." (PMID 40831500, 2025).
Parkinsonism (1 paper, 2022). Characteristic neurologic anomaly resulting from degeneration of dopamine-generating cells in the substantia nigra, a region of the midbrain, characterized clinically by shaking, rigidity, slowness of movement and difficulty with walking and gait. "No mutations have previously been described in this domain and both patients developed very similar phenotypes with parkinsonism and cognitive deterioration, which have not previously been reported in patients with pathogenic RNASEH1 mutations." (PMID 35947649, 2022).
thyroid cancer (1 paper, 2021). "Of these genes, Ribonuclease H1 (RNASEH1) caught our attention given its established role in DNA replication and repair and the recognized role of defective DNA repair in thyroid cancer progression." (PMID 34944959, 2021).
cancer (18 papers, 2014 to 2025). A tumor composed of atypical neoplastic, often pleomorphic cells that invade other tissues. "A pan-cancer analysis revealed that overexpression of RNASEH1 is associated with the regulation of the TME and poor prognosis, suggesting that RNASEH1 may promote BLCA immune escape by inhibiting anti-tumor immunity." (PMID 41019085, 2025). "This interaction increased telomeric DNA:RNA hybrids, induced telomeric defects, and elevated ALT-associated PML bodies formation in both telomerase- and ALT-positive cancer cells in an RNAseH1 dependent manner." (PMID 41325773, 2025). "Abnormal expression of RNASEH1 may lead to telomere dysfunction or excessive recombination, promoting the immortalization and invasiveness of cancer cells." (PMID 41019085, 2025). "RNaseH1 and RNaseH2 are the main RNase activities counteracting R-loop formation and upregulation of these enzymes may be a response of cancer cells to increased R-loop levels." (PMID 27725641, 2016). "It will be intriguing to test whether the proliferative potential of ALT cells is affected by long-term RNaseH1 overexpression both in culture and in animal models for cancer development." (PMID 25330849, 2014). "Among various cancer types, including UVM and SKCM, we observed a positive correlation between the expression of A3B and RNASEH1, a well-established nuclease that resolves R-loops." (PMID 37270643, 2023). "In agreement with a previous report on G-quadruplex binders and micronuclei in mammalian cancer cells, abolishing TOP1 poison-mediated increase of R-loops by RNaseH1 overexpression drastically reduced micronuclei levels." (PMID 35794238, 2022). "RNaseH1 has been shown to regulate TERRA levels and impact on the alternative lengthening of telomeres pathway, which maintains telomeres in a subset of cancers cells." (PMID 33357438, 2020).
tumor (9 papers, 2014 to 2025). "Uniform DNA MsPA oligonucleotides administered in complex with folate-containing liposomes demonstrated RNaseH1-mediated inhibition of primary tumor growth by downregulating miR-21 in tumors and increased biosynthesis of miR-21–regulated tumor suppressor proteins." (PMID 34417625, 2021). "Furthermore, overexpression of Rnaseh1, which degrades the RNA strand in RNA:DNA hybrids, decreases the levels of cytosolic ssDNA and dsDNA in tumor cells." (PMID 25623070, 2015). "Resolution of TERRA hybrids through enhancement of RNaseH1 activity might become an attractive procedure to fight ALT tumour progression with limited side effects upon treatment of patients." (PMID 25330849, 2014).
mitochondrial disease (6 papers, 2017 to 2023). "This is probably the case in mammals as well: in the mouse, liver degeneration caused by hepatic Rnaseh1 knockout was accompanied by mitochondrial dysfunction, and a point mutation in RNASEH1 produces a recognizable mitochondrial disease phenotype in humans." (PMID 30635398, 2019). "We screened 74 unrelated probands with genetically undetermined mitochondrial disease for RNASEH1 mutations." (PMID 28508084, 2017). "We aimed to determine the prevalence of RNase H1 gene (RNASEH1) mutations among patients with mitochondrial disease and establish clinically meaningful genotype-phenotype correlations." (PMID 28508084, 2017). "Although the c.424G>A p.Val142Ile mutation underpins all reported RNASEH1-related mitochondrial disease, haplotype analysis suggested an independent origin, rather than a founder event, for the variant in our families." (PMID 28508084, 2017). "Our data confirm that RNASEH1 mutations are an important cause of mitochondrial disease resulting from the secondary accumulation of multiple mtDNA deletions and that the phenotypic spectrum in adults is relatively benign." (PMID 28508084, 2017). "RNase H1 has a mitochondrial isoform and deleterious mutations in the RNASEH1 gene can disturb mtDNA replication and lead to mitochondrial disease." (PMID 28207748, 2017). "With the exception of SSBP1, a key component of the mitochondrial replication fork, to date, all nuclear genes directly involved in mtDNA replication (POLG, POLG2, TWINKLE, RNASEH1, DNA2, MGME1) have been associated with mitochondrial disease, mtDNA depletion, and/or mtDNA deletion." (PMID 31550237, 2020). "However, variants have also been described in the dual‐localised nucleases RNASEH1 and DNA2 that result in mitochondrial disease phenotypes." (PMID 37013609, 2023).
infection (3 papers, 2019 to 2022). The state of being infected such as from the introduction of a foreign agent such as serum, vaccine, antigenic substance or organism. "In contrast, cells transfected with a catalytically inactive mutant of RNaseH1 (pICE-RNaseH1-D10R, E48R-NLS) retain the ability to deacetylate H3K18 upon infection, which demonstrates that only catalytically active RNaseH1 blocks H3K18 deacetylation." (PMID 34929015, 2021). "During infection however, we find that blocking R-loop formation by overexpressing RNaseH1 leads to higher levels host DNA damage in response to L. monocytogenes, suggesting that R-loops play a protective role in this context." (PMID 34929015, 2021). "On the contrary, in cells overexpressing RNaseH1, which lack R-loops, the infection-induced interaction between SIRT2 and TDP-43 is inhibited suggesting that R-loops are required for SIRT2:TDP-43 complex formation in response to infection." (PMID 34929015, 2021). "By comparison, overexpression of RNaseH1 alone is sufficient to cause the same decrease in recovered bacterial colonies 24 hr post infection with no impact on infection at 6h." (PMID 34929015, 2021). "Likewise, blocking the formation of R-loops by overexpressing RNaseH1 also significantly increased the amount of γH2Ax detected in infected cells at 24 hours post infection." (PMID 34929015, 2021).
myopathy (1 paper, 2024). A disease of the muscle in which the muscle fibers do not function properly. "Recessive RNASEH1 variants cause adult-onset PEO, ptosis, myopathy, respiratory weakness, dysphagia, cerebellar disease, and neuropathy, with multiple mtDNA deletions." (PMID 38804971, 2024).
RNASEH1 also shares sentences with these, for which no sentence is quoted: Aicardi-Goutières syndrome (3 papers); progressive external ophthalmoplegia (2); viral infection (2); Aicardi–Goutieres syndrome (1); amyotrophic lateral sclerosis (1); asthma (1); developmental delay (1); gastric cancer (1); glioma (1); Hypercholesterolemia (1); lung disease (1); lung injury (1); melanoma (1); myotonic dystrophy (1); myotonic dystrophy type 1 (1); prion disease (1); Spasticity (1).